FGF7 (fibroblast growth factor 7)
Diseases named in the same sentence as FGF7 in open-access papers (continued):
Sharing a sentence is not in itself a finding about the gene and the disease.
tumor (continued). "The tumor samples expressed FGF7 at significantly higher levels when compared to the unmatched ascites samples (p < 0.0001)." (PMID 39886662, 2024). "Our findings indicate that higher FGF7 levels correlate with advanced tumor stages, increased vascular invasion, and poorer prognosis." (PMID 38491511, 2024). "Taken together, all these data suggest a potential role of CAF-derived FGF7 in driving ccRCC development by transmitting CAF signals to tumor cells." (PMID 39594574, 2024). "The results of cell co‐culture and spatial transcriptome assays confirmed that MUC1 and FGF7 mediated the communication between tumour cells and CAFs to a certain degree." (PMID 38778448, 2024). "To establish the role of CAFs-derived FGF7 and exclude the influence of tumor cells themselves, we employed siRNA-2 to knock down FGF7 expression specifically in A2780 and HO8910." (PMID 38491511, 2024). "Subsequently, ccRCC tumor cells paracrinally activated STAT3 signaling in CAFs to transcriptionally regulate FGF7 expression." (PMID 39594574, 2024). "Although not previously reported in MASLD, CHRDL2 is upregulated in a range of tumor tissues including HCC49, while STC1, CTGF50, GDNF and FGF7 are all linked to hepatic fibrogenesis." (PMID 37903863, 2023). "SLC38A2, DUSP1, and FGF7 expressed predominantly in tumor sites than that in normal lung in previous studies; however, they were expressed predominantly in the tumor stroma in this study." (PMID 36505794, 2022). "It has been reported that in thyroid epithelial cells, FGFR2-IIIb reduces the expression of FGF7 and increases the ratio of FGF4/FGF7 and couples epithelial signalling with expansion of stomal to favour tumour growth." (PMID 35459137, 2022). "In IECs, expression of STAT1 gene was also predicted to be upregulated by inflammatory cytokines IL1β and IFNγ and growth factor FGF7 identified as key molecules involved in tumor microenvironment." (PMID 34946170, 2021). "Next, we performed FGF5 and FGF7 IHC staining that revealed downregulation of these key FGF pathway molecules in anti-NCAM traeted tumor samples." (PMID 31477684, 2019). "These include FGF2 and FGF7 that promote tumor development, cancer cell proliferation, survival and wound healing responses, as well as TGFß2, which can promote cancer progression, cancer cell invasion and metastasis." (PMID 30325954, 2018). "HP also increased the mRNA and protein expression of FGF-7, key molecule in tissue repair and anagen induction in the dorsal skin lesions of C57BL/6 mice." (PMID 27386946, 2016). "FGF7 is only expressed by stromal cells and its receptor FGFR2IIb only by epithelial cells, indicating the role FGF7 in the beginning of tumor progression." (PMID 19721715, 2009). "In seeking the mechanism behind the impaired tumor growth and angiogenesis, we found that the production by CAFs of FGF-7, an epithelial cell growth factor, and of FGF-2, an angiogenic factor, was substantively diminished by imatinib." (PMID 18232728, 2008). "A statistical analysis of the distribution of colony sizes confirmed that heparin significantly reduced the size of the tumor cell colonies relative to the control or to FGF-7 treatment." (PMID 16176582, 2005). "By contrast, mast cell heparin at multiple doses significantly reduced the size and number of colonies of tumor cells co-cultured with fibroblasts, especially in the presence of FGF-7." (PMID 16176582, 2005). "Distinguished from FGF1, FGF7 may primarily act in synergy with progesterone to escalate tumor development and metastasis." (PMID 40826783, 2025). "Notably, FGF7 depletion blocked NIH/3T3-induced RENCA tumor growth, suggesting the tumor-promoting role of FGF7 in CAFs in vivo." (PMID 39594574, 2024). "Importantly, in vivo treatment with neutralizing antibodies targeting CAFs-derived FGF7 substantially reduced tumor growth." (PMID 38491511, 2024).
tumor (continued). "In addition, the in vivo ccRCC mouse model also substantiated the tumor-promoting role of CAF-derived FGF7, as its depletion significantly hindered tumor growth and the recruitment of M2 type macrophages." (PMID 39594574, 2024). "Then we utilized a 3D tumour–stromal organotypic co‐culture model and characterized the invasive phenotype of MFE296 cells in co‐culture with either WT or CRISPR/Cas9‐edited FGF7‐deficient (FGF7−/−) CAFs." (PMID 37165578, 2023). "Our demonstration that mutant FGFR2 enhances the sensitivity to FGF7‐induced ADAM17 activity provides an explanation of how these tumours might adapt in an environment with reduced growth factors." (PMID 37165578, 2023). "Furthermore, inhibiting the expression of FGF7 significantly reduces the division of tumour tissues." (PMID 35735060, 2022). "Our study demonstrates for the first time that the role of FGFR2 in ER+ BCa is dependent on the hormonal background of the tumour and relies on the involvement of the FGF7/FGFR2➔JunB axis in the regulation of PR modulatory effects on ER‐associated cellular events." (PMID 35726195, 2022). "We also identified the inhibition of FGF7 (a well-known fibroblast growth factor involved in tumor growth and invasion, and a potent epithelial cell-specific growth factor) by miR-15a; a previous study reported that the down-regulation of miR-15a progresses pancreatic cancer." (PMID 32913235, 2020). "Furthermore, the in vivo and in vitro experiments with PDX models also demonstrated miR-144 played anti-tumor roles through targeting FGF7 and CAV2." (PMID 32139705, 2020). "FGF7 is secreted by mesenchymal origin cells and acts as a paracrine cytokine targeting nearby cells via locally secreted signals, thus participating in immune reactions during tumor progression or inhibition." (PMID 33193571, 2020). "The FGF7 gene encodes keratinocyte growth factor (KGF), a member of the FGF family that are involved in various biological processes, including embryonic development, morphogenesis, cell growth, tumor growth, and tissue repair." (PMID 30777021, 2019). "One model that might explain this is that FGF22 might act to antagonise the tumour suppressive role of FGFR2b, by competing with the protective ligands FGF7 and FGF10." (PMID 22737238, 2012). "Notably, depletion of FGF7 could suppress ccRCC tumor growth by impeding M2 type macrophage infiltration." (PMID 39594574, 2024). "However, treatment with FGF7-Ab effectively reduced both tumor weight and volume." (PMID 38491511, 2024). "Moreover, although the study demonstrates the efficacy of neutralizing antibodies targeting CAFs-derived FGF7 in reducing tumor growth in vivo, more research is needed to evaluate the long-term safety, potential side effects, and optimal dosing strategies of such therapeutic interventions." (PMID 38491511, 2024). "Similarly, FGFR2 which promotes tumor stemness, could be targeted to block the FGF7 expressed from CAFs81." (PMID 37633924, 2023). "Our data indicated FGF7 could play a tumor-suppressive role in miR-107." (PMID 35783154, 2022). "Interestingly, AKT signalling is required for such FGF7-mediated regulation of tumour progression." (PMID 35193394, 2022). "Furthermore, the in vivo experiments in PDX models displayed the anti-tumor function of miR-144, which could be retrieved by overexpression of FGF7 and CAV2." (PMID 32139705, 2020). "Notable tumor-associated factors that appear to be highly expressed only in the Lewis lung cancer cell line that are also known to be involved in cancer, are osteopontin, kit ligand (stem cell factor), chemokine (CXC) ligand 1, pleiotropin, fibroblast growth factor 7, amphiregulin and epiregulin." (PMID 18489769, 2008). "We found that in both metabolism-related pathways, SLC5A3 + tumor cells exhibit significant communication with CAFs, particularly through the FN1/SDC2, FGF7/FGFR1, NGF/SORT1, and LRPAP1/LRP1 receptor-ligand pairs." (PMID 40652057, 2025).
tumor (continued). "Mechanistically, CAF-derived FGF7 triggers AKT activation to promote cell growth and cell invasion of ccRCC tumor cells." (PMID 39594574, 2024). "Together, our study demonstrates a signaling axis involving STAT3/FGF7/AKT that mediates the crosstalk between CAFs and ccRCC tumor cells, providing valuable insights for treating ccRCC patients." (PMID 39594574, 2024). "Our stromal score analysis showed a favourable link between the expressions of genes such as LRP1, FGF7, FOS, PI3, PAEP, and PDGFRA and tumour purity in our investigation of the effect of IRGs on OC’s TME." (PMID 39063239, 2024). "Further multivariate analysis unveiled significant insights: LRP1, PAEP, PI3, OBP2A, and IL27RA genes exhibited higher levels in the tumour group, whereas FOS, PDGFRA, and FGF7 showed higher expression in normal ovarian tissue (all p < 0.001)." (PMID 39063239, 2024). "As a response, ccRCC tumor cells stimulate STAT3-mediated transcriptional regulation, directly increasing FGF7 expression at the chromatin level in CAFs." (PMID 39594574, 2024). "For myofibroblasts, two subsets of this cell cluster (myoFib‐1 and myoFib‐2) were significantly upregulated in tumour tissues, and many oncogenes and CAF canonical genes showed high expression in the myoFib‐1 subset, especially the genes of FGF7 and THBS1." (PMID 38778448, 2024). "FGF7 showed positive correlations with markers like ENDRB and TGFB1, suggesting its influence on immune cell infiltration and activity in the tumour milieu." (PMID 39063239, 2024). "We found that FGF7+/THBS1+ myofibroblasts, MS4A4A+ macrophages, and ZEB1+ endothelial cells were tumour‐enriched cell subtypes in MCA, contributing to MCA progression through crosstalk with MUC1+ cancer cells." (PMID 38778448, 2024). "If these findings reflect the need to better define the appropriate dosing regimen and/or the expression (and secretion) by tumor cells of other phosphatonins (e.g., MEPE, FGF7, sFRP-4), it remains to be established." (PMID 37436671, 2023). "According to the data on THPA, most of these genes (VWF, GNG11, FGF7, and IL3RA) were also higher in PAAD tissues at the protein level (compared to non-tumor tissues)." (PMID 37070074, 2023). "In OS6, C25 actively secreted FGF7 and CTGF, which promoted CAF growth and tumor angiogenesis, and CXCL12, which interacted with CXCR4 to block and deplete the T-cell response." (PMID 35664733, 2022). "FGF7/FGFR2–JunB axis was shown to abrogate the modulatory effect of PR on BCa cells and promote progression of premenopausal tumours." (PMID 35726195, 2022). "C14 and C25 possessed FGF7, IGFBP4, and PDGFD paracrine functions, further promoting tumor growth and differentiation to the proliferative stage." (PMID 35664733, 2022). "Freshly isolated cells were additionally characterized for specific mRNA expression of tumor (GPC3, SPINK1, SPP1, KPNA2) and fibroblast (COL1A2, TWIST2, FGF7) marker genes using RT–qPCR." (PMID 36077764, 2022). "Most genes considered tumor specific in previous studies (tumor suppressor genes: SOCA3, KLF6, and PTGDS; tumor enhancer genes: SLC38A2, DUSP1, and FGF7) were expressed predominantly in tumor stroma or remission stroma than that in pre-treatment tumors." (PMID 36505794, 2022). "C25 actively secretes FGF7 and CTGF, which promote CAF growth and tumor angiogenesis, and CXCL12, which interacts with CXCR4 to block and deplete the T-cell response." (PMID 35664733, 2022). "Coculture conditions increased FGF-7 secretion and α-SMA expression, characterized by fibroblast activation and decreased epithelial marker E-cadherin in tumor cells." (PMID 33807441, 2021). "Although the role of FGFs in PDAC has been controversial, a set of good-prognostic LR pairs including FGF7, FGF10, and FGFR2 is proposed to exert a tumor suppressive function via reduced oxidative stress and activation of immune surveillance." (PMID 34522794, 2021).
tumor (continued). "The overexpression FGF7, FGF9, FGF14, FGF18 and IGF1 genes was found significant in early tumor grades." (PMID 34061869, 2021). "Upregulated expression of growth factors such as IGF1, FGF7, proteases such as MMP2, ECM constituents such as SPP1 also known as osteopontin and chemokine such as CXCL12 may indicate the presence of cancer-associated fibroblasts (CAFs) within the tumor microenvironment." (PMID 34946170, 2021). "Tumor cells expressed relatively high levels of EGFR, FGFR1, and FGFR2, while their corresponding ligands, such as COPA, GRN, HBEGF, FGF2, FGF7, and FGF18, were widely expressed in fibroblast cells." (PMID 34459128, 2021). "In the tumor microenvironment, tumor stroma surrounding PCa cells is enriched in fibroblasts that secrete AR-activating factors, such as EGF, FGF-7/KGF, IGF-1, and IL-6." (PMID 31484364, 2019). "Relatively high expression levels of FGF2, FGF7 and HGF are observed with fibroblasts established from tumor (HECAF2111) and three types of fibroblasts established from normal tissue (HFF75, HEF1173, and HEF2111)." (PMID 25884729, 2015). "In summary, the data highlight the importance of these IRGs in both promoting and preventing tumour progression by indicating a strong correlation between the expression level of genes such as LRP1, PI3, PAEP, FOS, FGF7, and PDGFRA and the degree of tumour immune infiltration in OC." (PMID 39063239, 2024). "Therefore, in our studies with tumor tissue the 3D culture was supplemented only with AREG and FGF7." (PMID 37776423, 2024). "This lack of significant differences in patient and tumor demographics indicates that the differences in survival between FGF7 low- and high-expressing groups are not due to any of these parameters." (PMID 39886662, 2024). "Since the communication between tumour cells and CAFs, unveiled by single‐cell transcriptomics, was mediated by MUC1 and FGF7/THBS1 to a certain degree, we examined the possibility of crosstalk between these two cell types in tumour tissues through expression information in spatial transcriptomics." (PMID 38778448, 2024). "Conversely, FGF7, FOS, and PDGFRA were less expressed in OC tumour samples than in normal tissues." (PMID 39063239, 2024). "A case showed a much higher secretion of FGF-7 in comparison with FGF-23, which enabled the clinician to correctly localize the FGF-7 producing tumor through an FGF-7 gradient rather than an FGF-23 gradient." (PMID 37623022, 2023). "The binding of FGF7 and FGFR2-IIIb could signal to SRC tyrosine kinase inducing phosphorylation of F-actin binding protein and cortactin, which promote the migration of tumour cells." (PMID 35459137, 2022). "In accordance with this, we demonstrate that both FGFR2 and FGF7 mRNA and protein are elevated in FP‐RMS cell lines compared to FN‐RMS cell lines and that FGF7 and FGFR2 mRNA as well as FGFR2 protein are elevated in FP‐RMS tumor samples." (PMID 34850536, 2022). "However, further experiments to genetically ablate FGF7 and FGFR2 in tumor xenografts are needed to confirm the proliferative role of this signaling axis in vivo." (PMID 34850536, 2022). "In our coculture model, KGF/FGF-7 secretion was upregulated; it has previously been postulated than CAFs could increase the viability and migration of tumor cells in a paracrine manner through this growth factor." (PMID 33807441, 2021). "As expected and in agreement with its proposed role as tumor suppressor, the overexpression of FGFR2b isoform slightly repressed Snail1 transcript expression, particularly in response to its ligand FGF7, while PKCε silencing did not affect this trend." (PMID 32429937, 2020). "Positive feedback between Fgf10 and Fgfr2-IIIb has previously been reported during salivary gland development, and in nonmalignant tumors, Fgf7-mediated FGFR2-IIIb expression is thought to play a tumor-suppressive role by promoting epithelial differentiation." (PMID 30695023, 2019).
tumor (continued). "FGF7 induced an increase of VEGF-A; thus, FGF-7 and its receptor FGFR2 IIIb may be involved in tumor angiogenesis in CRC." (PMID 22701813, 2012). "In summary, there is experimental evidence that FGF7 causes hyper-phosphaturia, but its association with TIO tumours may be as a mediator of tumour growth rather than as a phosphotonin." (PMID 38731904, 2024). "Tumoural and CAF scores were first calculated for the union of tumour and CAF spots based on the expression signatures of the genes MUC1 and FGF7/THBS1, respectively (here, fibroblasts and CAFs were combined as overall CAFs since the former might transform into the latter in tumour conditions)." (PMID 38778448, 2024). "FGF2, FGF7 and FGF10, as members of the fibroblast growth factor family, are involved in various biological processes, including embryonic development, cell growth, tissue repair, tumor growth and invasion, and have been reported to be critical targets in the fibrosis process." (PMID 37275903, 2023). "Such a result may be explained by the fact that MSCs play a supporting role in tumorigenesis through the secretion of factors such as IL6, IL8, VEGF, platelet-derived growth factor (PDGF), fibroblast growth factor (FGF)-7, TGF-β, and vimentin, supporting the growth and chemoresistance of the tumor." (PMID 36354566, 2022). "To further ensure that the tumor organoids were mainly composed of tumor cells, we used a medium not containing the growth factors necessary for the culture of normal lung organoids, such as fibroblast growth factor 7 (FGF7), FGF10, R-spondin, and Noggin15,25,26." (PMID 33972544, 2021). "We reported that expression of FGFR2 IIIb and one of its major ligands, FGF7, correlated with venous invasion, vascular endothelial growth factor A (VEGF-A) expression, and a poor prognosis and may promote venous invasion and tumor angiogenesis in pancreatic cancers." (PMID 22701813, 2012). "In this study, we demonstrate that FGF7 and FGF10, likely through FGFR2IIIb, induce downstream β-catenin activation and its nuclear translocation in both post-liver bud embryonic hepatoblasts and Mat1a−/− tumor initiating stem cell line via AKT-dependent phosphorylation of Serine-552." (PMID 23308088, 2012). "Notably, Fgf7 is upregulated in acute response to injury and thought to serve a protective role in DSS treated mice, however, it is also known to increase cell proliferation and may inadvertently act as a growth factor for tumor cells in the AOM/DSS setting." (PMID 35600339, 2022). "However, FGFR2 signaling in the tumor setting, where FGF2 and FGF7 are likely available from the surrounding microenvironment, may establish a paracrine pathway leading to continued cancer cell survival, growth and maintenance of transformation in the presence of EGFR targeted therapies." (PMID 21152424, 2010). "In GC, keratinocyte growth factor (KGF/FGF7) was the first to be shown to be secreted by gastric CAFs, although it was not expressed in GC tumor cells." (PMID 40075643, 2025). "Of the commonly enriched factors, FGF7, but not IL1B, showed significant effect on the proliferation of radiated tumor cells." (PMID 36261421, 2022). "Immunohistochemical staining in the present study also revealed the expression of FGF7 and FGF10 mainly in the stromal cells rather than the tumor cells." (PMID 24002438, 2013). "We noticed that STAT3-induced FGF7 expression in CAFs still occurs even in the absence of tumor cells because STAT3 inhibition by STAT3-IN-11 is sufficient to decrease FGF7 expression, suggesting a regulation of FGF7 expression by the basal activity of STAT3 in CAFs." (PMID 39594574, 2024). "Furthermore, immunohistochemical location of FGF7 and FGF10 was investigated mainly in the stromal cells rather than the tumor cells." (PMID 24002438, 2013).